STAT3 (signal transducer and activator of transcription 3)
Diseases named in the same sentence as STAT3 in open-access papers (continued):
Sharing a sentence is not in itself a finding about the gene and the disease.
melanoma (continued). "The STAT3 signaling pathway opens the gateway towards proliferation or apoptosis in dormant melanoma cells." (PMID 38419052, 2024). "In principle, quercetin inhibits the activation of Stat3 signal by interfering with phosphorylation and nuclear localization, making it potential to play a role in the prevention and treatment of melanoma." (PMID 39173044, 2024). "Our latest research results link the functions of intracellular NRN1 to the Notch and STAT3 signaling pathways in melanoma." (PMID 38705997, 2024). "Maciej’s group deletes STAT3 alleles in both CD4+ and CD8+ T cells prior to implantation, significantly inhibiting the growth of melanoma tumors in mice compared with STAT3+/+ CD8+ T cells." (PMID 38245798, 2024). "Intermediate STAT3 activation with a MITFlow phenotype is expected to keep melanoma cells in the dormant state." (PMID 38419052, 2024). "For instance, previous research has unveiled the role of the LHFPL3-AS1/miR-580-3p/STAT3 axis in promoting melanoma progression through the activation of the JAK2/STAT3 pathway." (PMID 38911376, 2024). "In summary, we were able to show that NRN1 links oncogenic signaling events between Notch and STAT3 in melanoma." (PMID 38705997, 2024). "B16 melanoma cells showed a reduction in RelA phosphorylation and, thus, in NFκB activity after STAT3 knockdown." (PMID 38571491, 2024). "G6PD promotes the proliferation of renal cell carcinoma and ectopically transplanted human melanoma cells in mouse models by regulating the signal transducer and activator of transcription 3 (STAT3) signaling pathway." (PMID 39516455, 2024). "IL-6 expression, driven by a newly identified interaction between endogenous E2F1 and active STAT3, leads to massive cytokine secretion via a positive feedback loop, both in melanoma and CD4+ T cells." (PMID 39544930, 2024). "Our group has shown that HDAC6is regulate PD-L1 in melanoma through STAT3, enhance the immunogenicity of melanoma cells, and increase the antitumor efficacy of anti-PD-1 by suppressing M2 macrophages." (PMID 38414061, 2024). "Our results first suggested that STAT3-targeted therapy of alantolactone combined with MAPKi is a new therapeutic strategy to overcome resistance to MAPKi in the treatment of melanoma." (PMID 38822350, 2024). "Napaubucasin, the Stat-3 inhibitor, completely depletes immunosuppression function as demonstrated in both mice and humans, and improves the survival rate within melanoma bearing mice." (PMID 39013845, 2024). "Nevertheless, E2F1-induced expression of IL6 and CD274, or elevated levels of STAT3, can mitigate the effect nurturing toward the Th2 direction in advanced stages of melanoma." (PMID 39544930, 2024). "In melanoma cells with BRAF mutations, PD-L1 expression is promoted through the activation of STAT3 and the downstream MAPK signal c-Jun, using MEK inhibitors significantly downregulates MAPK signaling and suppresses the production of PD-L1." (PMID 38762484, 2024). "The upregulated expressions of STAT3 related protein by STAT3, play positive roles in melanoma metastasis through promoting cell invasion and angiogenesis." (PMID 39525639, 2024). "Study also showed that activation of HER3/STAT3/SOX2 pathway was the mechanism of resistance against MAPKi in BRAF mutant melanoma cells." (PMID 38822350, 2024). "Regarding the study on the regulation of PD-L1 expression by HDAC6, it has been reported that when HDAC6 is highly expressed in melanoma, p-STAT3 and HDAC6 bind the promoter of PD-L1, promoting the transcription of PD-L1." (PMID 38231305, 2024). "Our previous study found that MAPKi treatment can activate JAK2/STAT3 signal in BRAF mutant melanoma." (PMID 38822350, 2024). "The combination of EGCG and metformin has been shown to suppress NF-κb, p65, and STAT3 signaling pathways in melanoma cells." (PMID 38398617, 2024).
melanoma (continued). "For example, in squamous cell NSCLC elevated levels of histone deacetylases (HDAC), such as HDAC3 and HDAC6, are detected, that are reported to upregulate PD-L1 expression by STAT3 signalling pathway in melanoma, osteosarcoma, and pancreatic cancer." (PMID 38541208, 2024). "As a ligand for TLR4, LPS promotes the proliferation and migration of TLR4-positive melanoma cells through signal transduction mediated by transcriptional activator 3 (STAT3) activation." (PMID 39723372, 2024). "Animal studies showed that prophylactic administration of luteolin controlled melanoma growth as well as Src/STAT3 signaling in both A375 and B16F10 melanoma-bearing mice." (PMID 38474604, 2024). "Apigenin stopped melanoma cell motility and invasion by downregulating STAT3 target genes (TWIST1, MMP-2, MMP-9, and VEGF)." (PMID 38398617, 2024). "Their experiments on B16F10 melanoma cells showcased the potential of both STAT3 siRNA-loaded and imatinib mesylate-loaded AuNPs to induce apoptosis and decrease cell viability independently." (PMID 40808797, 2024). "We previously showed that local treatments with CpG-Stat3 siRNA inhibit melanoma tumor growth by silencing Stat3 and activating tumor-infiltrating immune cells." (PMID 39618825, 2024). "The findings of the study propose that luteolin is capable of inhibiting STAT3 signaling in melanoma cells by suppressing its activation and promoting the degradation of STAT3 protein." (PMID 38474604, 2024). "Tumor cells from melanoma and many types of B cell lymphomas require persistently activated STAT3 for growth and/or survival." (PMID 39618825, 2024). "IL6RIL6 has shown favorable clinical efficacy as a whole‐cell melanoma vaccine, but it directly activates STAT3 phosphorylation, potentially inhibiting the IFN‐γ‐STAT1 pathway." (PMID 38973154, 2024). "Our data was consistent with previous studies, and we confirmed that MAPKi activates STAT3 signaling, upregulating the reprogramming factors Oct4 and Sox2 to resist MAPKi in melanomas." (PMID 38822350, 2024). "Our previous research found that targeted inhibition of the MAPK pathway promotes compensatory activation of STAT3 signaling in melanoma cells." (PMID 38822350, 2024). "In a conclusion, we first proposed STAT3 signaling activation by MAPKi, upregulated CSCs markers Oct4 and Sox2 as a mechanism of MAPKi-resistance in melanoma." (PMID 38822350, 2024). "Expression of STAT3-C, an oncogenic mutant form of STAT3 with constitutive activation, has been shown to increase tumor angiogenesis in mice transfected with B16 melanoma cells." (PMID 38339245, 2024). "A previous study found that TRIM14 activates the STAT3 pathway and induces tumor progression in melanoma." (PMID 37628777, 2023). "Activation of signal transducer and activator of transcription 3 (STAT3) signaling pathway: The EGFR-SRC family kinase (SFK)-STAT3 pathway is involved in vemurafenib resistance of melanoma." (PMID 37834284, 2023). "FLLL62, a more soluble analog for FLLL32, has specificity to STAT3 and promotes apoptosis in renal cell carcinoma and melanoma cell lines." (PMID 37173951, 2023). "The integration of the data presented in this study show that melanoma cells prompt microglia reprogramming via different variations of IL-6-mediated activation of STAT3." (PMID 37296634, 2023). "The regulation of STAT3 phosphorylation by OLT1177 and dexamethasone showed similar outcomes in murine melanoma and in human melanoma cell lines, implicating an evolutionary conservation of the STAT3 phosphorylation mechanisms between mouse and human." (PMID 36672229, 2023). "Protein expression at a STAT3/5 ratio and a phosphorylated STAT3/5 ratio is reduced in G6PD-deficient melanoma cells." (PMID 37185731, 2023). "Collectively, KIF22 knockdown suppressed the proliferation and glycolysis and facilitated the apoptosis of melanoma cells by inactivating EGFR/STAT3 signaling." (PMID 37944197, 2023).
melanoma (continued). "In fact, this cytokine can promote melanoma cell proliferation by increasing both IL-6 and the signal transducer and activator of transcription 3 (STAT-3)." (PMID 36978794, 2023). "Key transcription factors largely involved in pro-survival signaling in melanoma are signal transducer and activator of transcription (STAT)-3 and nuclear factor-kappa B (NF-κB), which were shown to be activated by phosphorylation in melanoma cells." (PMID 36674794, 2023). "Treatment of melanoma cells reduced STAT3 phosphorylation (Y705), inducing apoptosis via activation of Bax, reduction in Bcl-2 expression, and caspase-3 cleavage." (PMID 37181747, 2023). "STAT3 was constitutively activated in 40% of primary cutaneous melanomas and in 60% of melanomas that metastasized to regional lymph nodes." (PMID 37595251, 2023). "As such, increased phosphorylation of STAT3 has been demonstrated in melanoma cells resistant to vemurafenib, while the inhibition of STAT3 leads to a better response of these cells to vemurafenib." (PMID 36768289, 2023). "Remarkably, in a melanoma mouse model, the silencing of STAT3 expression can reverse the malignant phenotype." (PMID 36674794, 2023). "We next measured the effect of the IL-6/JAK/STAT3 inhibitors αIL-6R, Baricitinib, and Stattic on the proliferation of melanoma and microglia cells in 2D and 3D co-cultures." (PMID 37296634, 2023). "STAT3 activation promoted the accumulation of MDSCs in melanoma, and STAT3 inhibition weakened the suppressive function of MDSCs." (PMID 37006306, 2023). "We further showed that BET inhibitors sensitize melanoma cells to sunitinib by repressing GDF15 expression in a direct way by targeting its promoter or indirectly by targeting the IL6/STAT3 axis." (PMID 36720918, 2023). "In the antigen presenting cells, (APC)/Cytokine/Chemokine/Immune category, differences in IL-2, IL-3 and STAT3 signaling pathways in melanoma and Wnt, Rho GTPases MAPK4/6 signaling pathways in HD mDC were observed." (PMID 37938561, 2023). "TRIM14 overexpression activates the AKT and STAT3 pathways to boost melanoma proliferation, which corresponds to our study." (PMID 37628777, 2023). "Based on the identified peak, we designed primers for ChIP‐qPCR analysis, confirming that STAT3 binds to the GDF15 promoter in melanoma cells." (PMID 36720918, 2023). "We found that signal transducer and activator of transcription 3 (STAT3) activation is a central component in melanoma-microglia interactions, thus confirming published results in glioblastoma." (PMID 37296634, 2023). "STAT3 is found to be continuously active in melanoma cells and has a metastasis-promoting impact through the regulation of various genes." (PMID 36614303, 2023). "An increase in STAT3 phosphorylation was similarly observed in melanoma cells cultured in ultra-low attachment conditions with an anoikis resistant phenotype induced by overexpression of BRN2." (PMID 37181747, 2023). "Western blot analysis validated the RPPA findings: MCM from all four melanoma cell lines significantly upregulated STAT3 phosphorylation in microglia." (PMID 37296634, 2023). "IL-6/STAT3 pathway inhibitors diminished the pro-metastatic functions of microglia and reduced melanoma progression." (PMID 37296634, 2023). "Despite its short cytoplasmic tail of 49 amino acids, MUC21 has been reported to be associated with the STAT3/AKT and hedgehog pathways in glioblastoma and melanoma, respectively, leading to tumor cell proliferation and migration." (PMID 37858248, 2023). "ItP of such liposomes on melanoma-bearing mouse skin suppressed cancer progression compared with curcumin or STAT3 liposomes alone." (PMID 38140019, 2023). "A previous study found that STAT3 promoted melanoma metastasis by upregulating the expression of CEBPB family members." (PMID 37511481, 2023).
melanoma (continued). "FNDC3B has been reported to suppress invasion and metastasis by inhibiting the phosphorylation of STAT3 in melanoma cells." (PMID 38137388, 2023). "Taken together, these results demonstrated that STAT3 inhibition enhances melanoma cell sensitivity to sunitinib via suppression of STAT3 phosphorylation." (PMID 36720918, 2023). "Taken together, the present study is the first to demonstrate that KIF22 knockdown suppresses the proliferation and glycolysis and facilitates the apoptosis of melanoma cells by inactivating EGFR/STAT3 signaling." (PMID 37944197, 2023). "Immunoblotting was performed for the protein expression analysis of AKT and STAT3 in all three melanoma cell lines." (PMID 37895015, 2023). "Summing up, KIF22 depletion represses proliferation, inhibits glycolysis, and accelerates apoptosis of melanoma cells by inactivating EGFR/STAT3 signaling." (PMID 37944197, 2023). "Based on these results, and since microglial STAT3 is altered following interactions with several types of brain malignancies, we deduced that STAT3 is a pivotal factor in melanoma-microglia interactions." (PMID 37296634, 2023). "The activation of STAT3 protein is commonly observed in many tumors, including melanoma, which plays a chief role in regulating tumor cell growth and survival, angiogenesis, and evasion of immune surveillance." (PMID 36635761, 2023). "Additional oncogenic factors are employed with relation to STAT3 which together promote the growth of melanoma cells, their migration and survival." (PMID 36614303, 2023). "Specifically in melanoma, PTX has been tested as an adjuvant and neoadjuvant treatment at subtoxic doses and can inhibit melanoma tumor growth and angiogenesis by targeting the STAT3 signaling pathway." (PMID 37895943, 2023). "A study demonstrated increased STAT3 phosphorylation at Y705 in melanoma cell lines cultured in suspension conditions compared to adherent cells, driving upregulation of Bcl-2 and Mcl-1." (PMID 37181747, 2023). "To further validate the dependence on STAT3 phosphorylation, we used a selective STAT3 small molecule inhibitor (BP-1-102) in melanoma cells." (PMID 37444518, 2023). "Further in vivo study revealed that using microneedles that contained PEI carriers for STAT3 siRNA delivery in a mouse melanoma model resulted in STAT3 silencing and tumor growth inhibition." (PMID 38067351, 2023). "Whereas STAT1 abrogates growth and mediates anti-tumor effects, STAT3 promotes cell proliferation and tumorigenicity as it has been shown in melanoma and head neck squamous cell carcinoma." (PMID 37047709, 2023). "Increased pDC infiltration has been associated with poor outcomes in several cancers, including melanoma, where pDCs contribute to immune evasion via high indoleamine 2,3-dioxygenase (IDO) and phospho-STAT3 expression." (PMID 36821392, 2023). "We also generated sunitinib-resistant melanoma cells and found that the phosphorylation of STAT3 was increased in sunitinib-resistant melanoma cells." (PMID 36720918, 2023). "In melanoma, SNHG17 is upregulated by the transcription factor STAT3, contributing to melanoma progression by enhancing PI3K-AKT signaling and its growth-promoting effects that also facilitate cellular invasiveness and migration." (PMID 37755396, 2023). "Apigenin inhibited melanoma cell migration and invasion by downregulating STAT3 target genes (TWIST1, MMP-2, MMP-9, and VEGF)." (PMID 36829966, 2023). "Microglia cells exposed to melanoma-derived IL-6 exhibited upregulated levels of STAT3 phosphorylation and SOCS3 expression, which, in turn, promoted melanoma cell viability and metastatic potential." (PMID 37296634, 2023). "The baseline percentage of p-STAT3+ PBMCs was higher in melanoma patients compared to healthy donors." (PMID 37741983, 2023).
melanoma (continued). "Nonetheless, we found that SPAG9 ablation in HLA-G OE lung and melanoma BMICs diminished the expression of p-STAT3 despite the high HLA-G levels present in these cells, demonstrating that HLA-G modulates STAT3 signaling in BMICs via SPAG9." (PMID 36780531, 2023). "The combination of epigallocatechin-3-gallate (EGCG) and metformin has been observed to inhibit the phosphorylation levels of NF-κb p65 and STAT3 signaling pathways in melanoma cells." (PMID 36829966, 2023). "Subsequently, melanoma cells were treated with EGF or Colivelin to further elucidate the regulatory effect of KIF22 on EGFR/STAT3 signaling." (PMID 37944197, 2023). "An autoinflammatory loop has been reported in melanoma, where tumor cells produce IL-1β and IL-6 through IL-1β/IL-6/STAT3 axis allowing for the activation of MDSCs." (PMID 36932407, 2023). "EZH2 overexpressed in a wide variety of cancers with an active EMT and co-operated with signal transducer and activator of transcription 3 (STAT3) to regulate MHC class I antigen processing in melanoma, which mediated immune responses." (PMID 36823234, 2023). "One study examined the ability of the STAT3 inhibitor WP1066 to enhance T cell anti-tumor activity through Treg inhibition in patients with melanoma brain metastases." (PMID 37741983, 2023). "The studies on B16F10 melanoma cells showed that either the AuNPs-STAT3 siRNA or AuNPs-imatinib mesylate can induce apoptosis and decrease cell viability." (PMID 37765317, 2023). "Recent studies have identified a marked impact of STAT3 activity on the progression and development of melanoma, including promoting metastases." (PMID 36672229, 2023). "The cell viability of the co-delivery of curcumin and STAT3 siRNA using cationic liposomes in B16F10 mouse melanoma cells was inhibited considerably compared to either liposomal curcumin or STAT3 siRNA alone." (PMID 37570875, 2023). "In another study, PBMC samples from melanoma patients were analyzed for p-STAT3 expression after surgical resection and adjuvant nivolumab treatment." (PMID 37741983, 2023). "An independent study confirmed these findings, revealing that p-STAT3 (Y705) stimulated anoikis resistance of B16-F10 melanoma cells as part of the FAK, p-ERK1/2 and PPARγ signalling pathways." (PMID 37181747, 2023). "ItP of naked IL-10 siRNA or liposome-encapsulated STAT3 siRNA showed a significant RNAi effect on rat skin of an atopic dermatitis model or the skin of melanoma-bearing mice, respectively." (PMID 38140019, 2023). "Targeting STAT3 in murine melanoma and leukemia models increases the immunosurveillance of NK cells." (PMID 37501379, 2023). "•KIF22 depletion suppresses proliferation, glycolysis and facilitates apoptosis of melanoma cells by inactivating EGFR/STAT3 signaling." (PMID 37944197, 2023). "Nevertheless, our data indicate the downregulating effect of GP-2250 on proliferation, cell viability, apoptosis/necrosis, and AKT/STAT3 signaling in melanoma cells." (PMID 37895015, 2023). "We further demonstrated that STAT3 signaling was significantly activated in sunitinib-resistant melanoma cells and that inhibition of STAT3 enhanced the sensitivity of melanoma to sunitinib." (PMID 36720918, 2023). "STAT3 has been extensively studied in the context of melanoma, where its constitutive activation is shown to promote melanoma cell proliferation, metastasis and invasion, and contribute to immune evasion by stimulating persistent expression of VEGF." (PMID 37181747, 2023). "Control and STAT3-silenced melanoma cells were incubated with sunitinib or cotreated with sunitinib and BET inhibitors." (PMID 36720918, 2023). "Consistently, melanoma patients with higher level expression of STAT3 or GZMB suggested a good prognosis." (PMID 35145233, 2022). "Our data showed that STAT3 phosphorylation level was significantly reduced in melanoma cells exposed to apatinib and WZB117 combination treatment compared to monotherapies." (PMID 36188586, 2022).